ATAD3C (ATPase family AAA domain containing 3C)
Synonyms: FLJ34599
Tractability: PROTAC: ubiquitination databases record sites on it; its protein half-life has been measured.
Gene: Protein-coding gene on chromosome 1 (1,449,689 to 1,470,163, forward strand). Ensembl gene ENSG00000215915.
Subcellular location (Human Protein Atlas): Mitochondria
Gene Ontology:
Molecular function: ATP binding; ATP hydrolysis activity
Biological process: mitochondrion organization
Cellular component: mitochondrion
Genetic constraint (gnomAD): Loss-of-function variants: 38 observed, 43.31 expected, observed/expected ratio (o/e) 0.88, 90% interval 0.68 to 1.15. The upper end of that interval is the gene's LOEUF score, 1.15, which puts it in group 5 of 6, group 1 being the genes least tolerant of losing a copy. Missense variants: 552 observed, 529.09 expected, observed/expected ratio (o/e) 1.04, 90% interval 0.97 to 1.12. Synonymous variants: 218 observed, 214.15 expected, observed/expected ratio (o/e) 1.02, 90% interval 0.91 to 1.14.
Homologues: Orthologues: chimpanzee ATAD3C (71% identical). Paralogues in human: ATAD3B (89% identical), ATAD3A (89% identical).
Diseases named in the same sentence as ATAD3C in open-access papers:
ATAD3C is named in the same sentence as 2 diseases in open-access papers, as found by Europe PMC text mining. Sharing a sentence is not in itself a finding about the gene and the disease.
ATAD3C shares sentences with these, for which no sentence is quoted: cardiomyopathy (1 paper); neurological disorders (1).